PTGFR (prostaglandin F receptor)
Description:
Receptor for prostaglandin F2-alpha (PGF2-alpha). The activity of this receptor is mediated by G proteins which activate a phosphatidylinositol-calcium second messenger system. Initiates luteolysis in the corpus luteum (By similarity). Isoforms 2 to 7 do not bind PGF2-alpha but are proposed to modulate signaling by participating in variant receptor complexes; heterodimers between isoform 1 and isoform 5 are proposed to be a receptor for prostamides including the synthetic analog bimatoprost.
Synonyms: FP
Tractability: Small molecule: an approved drug acts on it; a structure with a bound ligand is known; a high-quality ligand is known; it belongs to a druggable protein family. Antibody: its Gene Ontology location is reachable by antibodies, with high confidence; UniProt places it where antibodies can reach, with medium confidence; UniProt predicts a signal peptide or a membrane-spanning region. PROTAC: a small molecule that binds it is known.
Target class: Lipid-like ligand receptor (family A GPCR); Membrane receptor; Prostanoid receptor; Small molecule receptor (family A GPCR); Family A G protein-coupled receptor
Chemical probes: BAY-6672 (high quality), CLOPROSTENOL, DINOPROST
Gene: Protein-coding gene on chromosome 1 (78,303,884 to 78,540,701, forward strand). Ensembl gene ENSG00000122420.
Subcellular location: Cell membrane
Pathways (Reactome):
Signal Transduction: G alpha (q) signalling events; Prostanoid ligand receptors
Gene Ontology:
Molecular function: prostaglandin F receptor activity; protein binding; G protein-coupled receptor activity
Biological process: cellular response to prostaglandin D stimulus; positive regulation of cell population proliferation; adenylate cyclase-activating G protein-coupled receptor signaling pathway; G protein-coupled receptor signaling pathway; inflammatory response; parturition; positive regulation of cytosolic calcium ion concentration; maternal process involved in female pregnancy; positive regulation of gene expression; response to estradiol; response to lipid
Cellular component: cytoplasm; extracellular region; plasma membrane; membrane
Genetic constraint (gnomAD): Loss-of-function variants: 15 observed, 27.26 expected, observed/expected ratio (o/e) 0.55, 90% interval 0.37 to 0.85. The upper end of that interval is the gene's LOEUF score, 0.85, which puts it in group 3 of 6, group 1 being the genes least tolerant of losing a copy. Missense variants: 369 observed, 450.06 expected, observed/expected ratio (o/e) 0.82, 90% interval 0.75 to 0.89. Synonymous variants: 165 observed, 160.68 expected, observed/expected ratio (o/e) 1.03, 90% interval 0.9 to 1.17.
Homologues: Orthologues: chimpanzee PTGFR (99% identical), macaque PTGFR (98% identical), dog PTGFR (93% identical), rabbit PTGFR (93% identical), guinea pig PTGFR (92% identical), mouse Ptgfr (89% identical), rat Ptgfr (87% identical), pig PTGFR (86% identical), tropical clawed frog ptgfr (69% identical), zebrafish ptgfr (50% identical), Drosophila melanogaster CG7497 (23% identical). Paralogues in human: PTGER1 (37% identical), PTGER3 (32% identical), TBXA2R (32% identical), PTGER4 (24% identical), PTGIR (23% identical), PTGDR (21% identical), PTGER2 (21% identical).
Diseases named in the same sentence as PTGFR in open-access papers:
PTGFR is named in the same sentence as 34 diseases in open-access papers, as found by Europe PMC text mining. Sharing a sentence is not in itself a finding about the gene and the disease. The quoted sentences say what the papers report.
glaucoma (7 papers, 2021 to 2025). Increased pressure in the eyeball due to obstruction of the outflow of aqueous humor. "A negative association was found between single nucleotide polymorphisms of PTGFR (rs11578155 and rs6672484) and the response to prostaglandin analogs in patients with glaucoma." (PMID 36313286, 2022). "Up to now, six studies reported the association between the SNPs in PTGFR (rs1073611, rs10786455, rs11578155, rs12093097, rs35586449, rs3753380, rs376635, rs3766354, rs3766355, rs6672484, and rs6686438) and glaucoma with the treatment of latanoprost." (PMID 36313286, 2022). "Rs1045642 in ABCB1, rs4241366 in SLCO2A1, rs9503012 in GMDS, rs10306114 in PTGS1, rs11568658 in MRP4, rs10786455 and rs6686438 in PTGFR were reported to be positive with the response to prostaglandin analogs in patients with glaucoma." (PMID 36313286, 2022). "Lastly, prostaglandin analogues, the most common IOP-lowering treatment for glaucoma, work by upregulation of MMPs via the prostaglandin F receptor." (PMID 35897642, 2022). "To date, the response to latanoprost of patients with glaucoma and ocular hypertension, is reported to be associated with the genetic polymorphism of seven genes (ABCB1, SLCO2A1, AFAP1, GMDS, PTGS1, MRP4, and PTGFR)." (PMID 36313286, 2022). "Patients aged 18 years or older who were diagnosed with glaucoma between November 2018 and August 2020, and prescribed omidenepag isopropyl (OMDI), prostaglandin F receptor agonists (FP), or beta-blockers (BB) monotherapies were included." (PMID 41198761, 2025). "Various SNPs in the PTGFR, ADRB2, and CYP2D6 genes can affect the response to pharmacologic therapy in glaucoma." (PMID 40142989, 2025).
endometrial adenocarcinoma (3 papers, 2008 to 2023). "PGF2α is upregulated in human endometrial adenocarcinoma, and PGF2α binding to PTGFR promotes the growth and production of PGE and PGF in tumor cells." (PMID 38188684, 2023). "PGF2α has been reported to bind PTGFR and stimulate the proliferation of endometrial adenocarcinoma cells." (PMID 38188684, 2023). "Overexpression of PTGFR was found to be a novel marker in endometrial adenocarcinoma and renal cell carcinoma." (PMID 32724813, 2020). "Prostaglandin F2 alpha receptor (PTGFR), a membrane receptor for prostaglandin F2 alpha, has been reported to be related to tumorigenesis and progression in endometrial adenocarcinoma." (PMID 32724813, 2020).
abortion (1 paper, 2021). the ending of pregnancy by removing a fetus or embryo before it can survive outside the uterus. "Not only PGF2α but also PTGFR increased significantly in the uterus of RSA rats, which combined and interacted with each other to contract the uterus and lead to abortion." (PMID 33868179, 2021).
breast carcinoma (1 paper, 2022). "Differentially expressed genes, especially those in five modules, including OAS1, IFI27, LPAR1, PTGFR, ITGB4, and ITGA6, might participate in the epithelial-mesenchymal transition process in breast cancer cell line DKTA." (PMID 36289533, 2022).
breast tumor (1 paper, 2022). "This can be traced in contrasting pairs such as miR-19a/PTGER2 (pancreatic tumor); miR-421/PTGER2 (uterine tumor); miR-590/PTGFR (uterine and breast tumor); miR-20a/PTGER3 (uterine tumor)." (PMID 35453789, 2022).
colorectal tumors (1 paper, 2015). "Interestingly, although the observed mutation rates are very low, there still seems to be significant poor prognosis associated with mutations in PTGFR, one of the genes most predominantly hypermethylated and downregulated in colorectal tumors." (PMID 26207152, 2015).
diabetes (1 paper, 2023). "Since diabetic nephropathy is also a microvascular complication of diabetes as retinopathy and excessive angiogenesis also occurs in diabetic nephropathy, it is possible that the PGF2α/PTGFR axis may be involved in the pathogenesis of diabetic retinopathy." (PMID 36511116, 2023).
endometriosis (1 paper, 2022). The growth of functional endometrial tissue in anatomic sites outside the uterine body. "In this study, we screened four characteristic genes of endometriosis (ACLY, PTGFR, ADH1B, and MYOM1) by using the full transcriptome sequencing data of clinical samples and public database resources." (PMID 35938015, 2022). "Hence, four genes were defined as characteristic genes for endometriosis by overlapping the genes derived from these two algorithms, including ACLY, PTGFR, ADH1B, and MYOM1." (PMID 35938015, 2022).
glioma (1 paper, 2024). A benign or malignant brain and spinal cord tumor that arises from glial cells (astrocytes, oligodendrocytes, ependymal cells). "Using Per2-fusion luciferase-expressing C6 rat glioma cells (Per2::luc C6 cells), we synchronized cell clock genes with dexamethasone, added PTGFR agonists at different times, and tested their effects on the periodicity of Per2::luc activity." (PMID 38339119, 2024).
hemoglobinopathy (1 paper, 2022). "The expression gene analysis showed that PTGFR (downregulated) and GPR56 (upregulated) are differentially expressed in placentas of women with sickle cell anemia as well as SPOCK1 (downregulated) and ADCY4 (upregulated) in placentas of women with hemoglobinopathy HbSC." (PMID 36129958, 2022).
keloid (1 paper, 2024). An irregularly shaped, elevated mark on the skin caused by deposits of excessive amounts of collagen during wound healing. "LIF was significantly up-regulated in keloids compared to normal skin, while PTGFR and RBP5 were down-regulated in keloids." (PMID 39014455, 2024). "In conclusion, the present study provided new immune signatures (PTGFR, RBP5, and LIF) for keloid diagnosis and treatment using multiple bioinformatic analyses and machine learning algorithms." (PMID 39014455, 2024). "In summary, the present study provides novel immune signatures (PTGFR, RBP5, and LIF) for keloid diagnosis and treatment, and identifies retinoic acid as potential anti-keloid drugs." (PMID 39014455, 2024). "At the same time, PTGFR and RBP5 were down-regulated in keloid." (PMID 39014455, 2024).
melanoma (1 paper, 2022). A malignant, usually aggressive tumor composed of atypical, neoplastic melanocytes. "Mutation frequency of TBXAS1, PTGIS, AKR1C3, PTGDR, PTGFR and PTGER3 genes in melanoma were 5–6%, 5–7%, 2.8–5%, 3–4%, 7–9%, 2.1–5%, respectively." (PMID 35453789, 2022). "muTARGET web-based tool allowed us to predict genes, which expression patterns can be associated with genetic polymorphism in group #1 (TBXAS1, PTGIS, and AKR1C3) or group #2 (PTGDR, PTGFR, and PTGER3) in melanoma." (PMID 35453789, 2022).
proliferative diabetic retinopathy (1 paper, 2023). Advanced retinopathy due to diabetes mellitus characterized by the formation of new vessels in the retina. "Here we showed that PGF2α/PTGFR axis promotes to oxygen‐induced retinopathy (OIR) in mice, and PTGFR receptor may represent a novel therapeutic target for pathological retinal neovascularization, particularly for proliferative diabetic retinopathy (PDR)." (PMID 36511116, 2023).
retinal disease (1 paper, 2023). "Targeting the PTGFR and its downstream pathway may therefore serve as a novel approach for proliferative retinal disease management, independent of VEGF." (PMID 36511116, 2023).
thyroid cancer (1 paper, 2023). "Regarding PTGFR and DPP6, to our knowledge, both genes fail to be associated with thyroid cancer to date." (PMID 37372430, 2023). "The results revealed that all the genes are highly relevant in the context of thyroid cancer and, more particularly interesting, PTGFR and DPP6 have not yet been associated with the disease up to date, thus making them worthy of further investigation as to their relationship to PTC." (PMID 37372430, 2023).
Ureteral obstruction (1 paper, 2012). Obstruction of the flow of urine through the ureter. "Prostaglandins play an important role in ureteral obstruction, but the detailed expression profiles of the prostaglandin receptors (PTGER1, PTGER2, PTGER3, PTGER4, PTGFR) remain unknown in the different parts of the human ureter." (PMID 23227994, 2012).
tumor (6 papers, 2013 to 2023). "The result showed that PTGFR had a lower expression level in tumor tissue, yet LILRA2 and KCNA1 were highly expressed in tumor tissue." (PMID 36091124, 2022). "Apropos tumor stage, it is seen that GABRB2, DPP6 and PTGFR might have some relation with the progression of the disease." (PMID 37372430, 2023). "The opposite trend was observed with PTGER4, PTGDS, PTGER3, PTGIS, PTGFR, and PTGS1 genes, which showed overexpression in the adjacent non-tumor tissue, followed by downregulation in the tumor." (PMID 26207152, 2015). "Most of the transcriptomic signatures (without subgroup analysis) still show acceptable tumor specificity with the exception of the signature containing PTGDS, CBR3, PTGIR, PTGFR, PTGDR2, and PTGER3 genes in HNSC tumor, which is similar to other tumors (BRCA, CESC, LUAD, SARC, and UCES)." (PMID 35453789, 2022).
cancer (5 papers, 2013 to 2023). A tumor composed of atypical neoplastic, often pleomorphic cells that invade other tissues. "However, the roles of PGF and its receptor PTGFR (also called FP) in cancer development are less clear." (PMID 38188684, 2023). "PTGDR, PTGDR2, PTGER1, PTGER3, and PTGFR genes have the median expression value of about 1 FPKM (Fragments Per Kilobase Million), while other genes are expressed in the range of 1–5 FPKM, regardless of cancer specificity." (PMID 35453789, 2022).
cardiovascular disease (1 paper, 2018). "Analysis of the interactome and disease-related network on the 44-dysregulated genes identified HDAC9, SMAD4, PTGFR, and PRKCE as the highest scoring genes within the cardiovascular disease category." (PMID 29520069, 2018).
pancreas (1 paper, 2015). "Indeed, not only colorectal, but also liver, stomach, and pancreas tumors present high rates of hypermethylation of PTGIS, AKR1B1, PTGER3, and PTGFR." (PMID 26207152, 2015).
proliferative retinopathy (1 paper, 2023). "CXCR2 was the dominant ELR+ CXC chemokine receptor expressed in retinal ECs, and CXCR2 deficiency abolished the therapeutic effect of PTGFR inhibition on retinopathy in OIR mice." (PMID 36511116, 2023). "In summary, our study demonstrated that activation of the PGF2α/PTGFR axis accelerates experimental proliferative retinopathy through the secretion of ELR+ CXC chemokines via FOS‐mediated transcriptional regulation." (PMID 36511116, 2023). "PTGFR deletion in ECs mitigated oxygen‐induced retinopathy in mice mainly by suppressing EC proliferation." (PMID 36511116, 2023). "Therefore, the activated PGF2α/PTGFR axis in ECs may directly contribute to the pathogenesis of proliferative retinopathy." (PMID 36511116, 2023).
PTGFR also shares sentences with these, for which no sentence is quoted: colon cancer (1 paper); colorectal cancer (1); diabetic nephropathy (1); diabetic retinopathy (1); heart failure (1); open-angle glaucoma (1); postpartum hemorrhage (1); prostate carcinoma (1); renal cell carcinoma (1); Sepsis (1); sickle cell anemia (1); type 2 diabetic (1); uterine tumor (1).